BRCA1 (BRCA1 DNA repair associated)
Diseases named in the same sentence as BRCA1 in open-access papers (continued):
Sharing a sentence is not in itself a finding about the gene and the disease.
breast cancer (continued). "Further, it was observed that tumors established in the rats with introduced double knockout BRCA1 and SHLD2 breast cancer cells were significantly smaller after treatment with ART812." (PMID 36613762, 2022). "However, HspBP1 did not affect tumorigenic properties in BRCA1-deficient breast cancer cells." (PMID 35387978, 2022). "In summary, the Talazoparib Beyond BRCA trial is a prospective study that identifies the sensitivity of gPALB2 breast cancers to PARP inhibition and highlights the core role of PALB2 in BRCA1- and/or BRCA2-mediated HR DNA repair in human breast cancers." (PMID 36253484, 2022). "This places the receptor phenotypes of the MINAS breast cancers intermediate between that of BRCA2 only and BRCA1 only breast cancers, and would be consistent with an independent rather than synergistic effect in BRCA1/BRCA2 MINAS." (PMID 34983940, 2022). "BRCA‐1, which contributes to HR in S/G2‐phase cells and NHEJ in G1‐phase cells, negatively regulates carcinogenesis, especially in breast cancer and ovarian cancer." (PMID 35735060, 2022). "The significantly higher response rates in patients with BRCA1/2m tumors was observed only in the breast cancer arm, with ORR of BRCA1/2m of 74% vs. wtBRCA1/2 11%." (PMID 36533080, 2022). "For example, lncRNA 01638 downregulation repressed the expression of DNMT1, DNMT3A and DNMT3B, and increased the expression of PTEN and BRCA1, resulting in inhibition of proliferation and invasion in HER2-positive breast cancer cells." (PMID 35620052, 2022). "Women with persistently high cancer worry scores were more likely to be below age 35 (BRCA1) or 40 (BRCA2) years, be unemployed, have had breast cancer, be lower educated and have shorter time between BRCA1/2-PV diagnosis and surgery." (PMID 34997316, 2022). "Functional defects in BRCA1 and BRCA2 are also found in approximately 4.2% of unselected Japanese patients with breast cancer." (PMID 34467476, 2022). "One of the more recent studies is the Olympya trial, where patients with HER2-negative early breast cancer and germline PVs or LPVs in FANCD1/BRCA2 and FANCS/BRCA1 are treated with adjuvant Olaparib." (PMID 36091172, 2022). "In the past, genetic testing was based only on the high-penetrance genes such as BRCA1 and BRCA2, which account for around 12 to 15% of ovarian cancers (OC) and 3 to 5% of breast cancers (BC) in most populations worldwide." (PMID 35886069, 2022). "Here we expand on these studies by showing Brca1 alters the expression of Tgfβr2 to elevate Tgfβ signaling and EMT in breast cancer cells." (PMID 35236825, 2022). "It was reported that expression of BRCA1 and BRCA2, both let-7a targets, was down-regulated after delivery of magnetic core–shell nanoparticle (MCNP)/let-7a constructs to breast cancer cells." (PMID 35328651, 2022). "Hwang reported a median age of 59 years in BRCA1 and 49 years in BRCA2, for any type of breast cancer." (PMID 36349178, 2022). "For example, the susceptibility gene 1 (BRCA1) C-terminal (BRCT) domain binds to p-ACC1 to from BRCA1/p-ACC1 complex, which prevents dephosphorylation of p-ACC1 and constantly suppress the activity of ACC1 to reprogram the metabolism network in breast cancer." (PMID 35359351, 2022).
breast cancer (continued). "Consistent with its tumor suppressor role, wild-type BRCA1 was shown to repress IGF1R gene transcription and promoter activity as well as endogenous IGF1R levels in breast cancer cells." (PMID 35432218, 2022). "Early studies on the role of aberrant DNA methylation in breast cancer focused on increased DNA methylation (DNA hyper-methylation) of CpG islands of key cancer genes, including ESR1 and BRCA1." (PMID 35158742, 2022). "The detection of PVs in BRCA1 and BRCA2 was, as expected, strongly correlated with breast cancer pathology and family history." (PMID 33758026, 2022). "In South-Eastern Norway, genetic testing for BRCA1 and BRCA2 is offered to breast cancer patients by their treating surgeon or oncologist." (PMID 35123550, 2022). "BRCAness phenotype in breast cancer has been shown to be highly correlated with the response to platinum-based chemotherapy and PARP inhibitors in BRCA1 and BRCA2 germline wild-type triple negative breast cancer (TNBC)." (PMID 35855837, 2022). "Talazoparib, a PARP inhibitor, is active in germline BRCA1 and BRCA2 (gBRCA1/2)-mutant advanced breast cancer, but its activity beyond gBRCA1/2 is poorly understood." (PMID 36253484, 2022). "Further, in pathways curated from chemical and genetic perturbation experiments, we found that the genes were enriched for genes highly positively co-expressed with BRCA1 and BRCA2, two genes well reported to be involved in breast cancer." (PMID 36584096, 2022). "In breast cancer, the interaction between GADD45 and BRCA1 gene has been suggested to influence the pathogenesis of the disease most likely via triggering the nucleotide excision repair mechanisms." (PMID 36185256, 2022). "Since DCAF8L1 is an X-linked gene, and many breast cancers display X chromosome misbehavior including X chromosome duplication and loss of XCI, our study may have important implications in understanding the relationship between BRCA1, X chromosome instability and breast tumorigenesis." (PMID 35280675, 2022). "In BRCA1 or BRCA2 mutants, these errors lead to chromosomal re-arrangements and shifts typical of hereditary breast cancers." (PMID 36010882, 2022). "By contrast, there was a negligible increase in survival among carriers of BRCA1 and BRCA2 aged over 35 years with luminal breast cancer in exon 11 who underwent any secondary prevention strategy compared with surveillance." (PMID 36580360, 2022). "The promoters of several known tumor suppressor genes (e.g., ATM, BRCA1, and PALB2) were all hypermethylated in WTC exposed breast cancer cases compared to the unexposed group." (PMID 35564499, 2022). "Furthermore, another group of researchers using DHPLC analysis of 210 breast cancer families (129 families have no mutations in BRCA1 or BRCA2) of Australian ethnicity have identified a set of nine coding mutations of BARD1 including two novel variants (Thr598Ile and Ile692Thr)." (PMID 35650591, 2022). "However, when BRCA1 is mutated in breast cancer cells, it can no longer degrade the ERM complex." (PMID 35740092, 2022). "In the Chinese cancer patients, a study showed that the prevalence rate was 5.53% for BRCA1/2 (43.7% in BRCA1 and 56.3% in BRCA2) in unselected breast cancer patients." (PMID 36439508, 2022). "A future sequencing study of the entire PPARGC1A locus in large ovarian and breast cancer cohorts, particularly in cancer patients with family history, is warranted to further validate our finding of PPARGC1A as a BRCA1/2 genetic modifier." (PMID 35625955, 2022).
breast cancer (continued). "The aim of this study was therefore, to determine the prevalence of (rs80357867, rs80358086) of the BRCA1 gene and (rs80359592) of the BRCA2 gene, with a view to contributing to breast cancer prevention in Burkina Faso." (PMID 35950060, 2022). "In line with our observations in WB1P and WB1P-Myc mammary tumors, expression of CCL5 and pSTAT1 was induced upon BRCA1/2 depletion, and was suppressed in MYC-overexpressing BT-549 cells." (PMID 36323660, 2022). "The observation of our study supports the lifelong follow-up in BRCA1 and BRCA2 carriers as breast cancer can be diagnosed as late as approximately 80 years in BRCA2 carriers." (PMID 35469032, 2022). "LncRNA MALAT1 increased the expression of DNMT1, DNMT3A and DNMT3B and inhibited the BRCA1 and PTEN expression, leading to regulating of herceptin sensitivity in HER2-positive breast cancer." (PMID 35620052, 2022). "“Burden of cost” (33%), “feeling no need since already diagnosed with breast cancer” (25%), “fear of discovering a genetic mutation” (23%), and “do not trust genetic test results” (16%) were reported as the main barriers among individuals who did not intend to undergo BRCA1/2 testing." (PMID 35629239, 2022). "Our studies demonstrate that BRCA1 protein expression is required for the IR-induced activation of ERK1/2 signaling in breast cancer cells, and conversely, ERK1/2 activity supports the protein stability of BRCA1 in the irradiated breast cancer cells." (PMID 35328212, 2022). "In addition, 90% of BRCA1-associated breast cancers reveal negative ER expression." (PMID 35402620, 2022). "It has been reported that PARP inhibitors are more effective for patients with BRCA1- and BRCA2- mutant ovarian cancer than for breast cancers, which shows that genetic context is crucial for functional genomic target screening." (PMID 35055413, 2022). "Women with a BRCA1 mutation have a cumulative risk of OC of 44% until age 80 years, of BC of 72% and of contralateral breast cancer (CBC) of up to 48%, depending on the age of primary BC onset." (PMID 34767113, 2022). "Although BRCA1 and BRCA2 have been studied extensively, other genes are also involved in the occurrence of breast cancer." (PMID 35785170, 2022). "Findings showed that BRCA1 and 2 inactivation frequently led to higher HRD score in ovarian and breast cancers." (PMID 35785170, 2022). "WES on 290 BRCA1/BRCA2-negative Singaporeans with early-onset breast cancer and/or a family history of breast cancer was done." (PMID 36424660, 2022). "Both BRCA1 and BARD1 are subject to post-translational modification, where the phosphorylation of various residues in each protein have been detected in breast cancer tissue and leukemia cells." (PMID 35327659, 2022). "Among the 70 patients with BRCA1 LGR, patients with ovarian cancer accounted for the largest proportion (33/70, 47.1%), followed by breast cancer (12/70, 17.1%) and lung cancer (9/70, 12.9%)." (PMID 36147908, 2022). "In a Swedish study, the prevalence of BRCA1 and BRCA2 PVs was 1.8% of all unselected breast cancer patients." (PMID 35469032, 2022).
breast cancer (continued). "The inherited variation in the genetic sequence of BRCA1, BRCA2 genes accounts for 5% to 10% of all breast cancers and was identified primarily among Black and Hispanic breast cancer patients." (PMID 35269622, 2022). "BRCA1 LGR more frequently occurred in ovarian cancer (1.31%, 33/2526), followed by breast cancer (0.67%, 12/1788) and neuroendocrine cancer (0.66%, 1/152)." (PMID 36147908, 2022). "In this study, we investigated T-96's antitumor activity on two breast cancer cell lines, SUM-1315 cell line, a highly metastatic and BRCA1 mutant TNBC cell line, and MCF-7 cell line, a lowly metastatic and ER-positive breast cancer cell line." (PMID 36276611, 2022). "Interestingly, we found that Tgfβr2 mRNA did not elevate in K14-Cre;p53f/f;Brca1f/f mammary tumors, suggesting that upregulation of Tgfβr2 may be unique to Brca1 germline mutant tumors also deficient in p18." (PMID 35236825, 2022). "We found HR mutations in approximately 15% of the patient cohort (n = 85), compared with 23% for BRCA2, 13% for GATA3, 7% for BRCA1, and 3% for PTEN in the same breast cancer patient cohort." (PMID 36230572, 2022). "Cadherin 1 (CDH1), CDKN2A, the runt‐related transcription factor 3 (RUNX3), BRCA1 and RASSF1A are reported to be suppressed by DNMT3B‐dependent DNA hypermethylation in gastric or breast cancers." (PMID 34133843, 2022). "From 12,182 abstracts, 15 studies measuring gene penetrance covering 5 putative male breast cancer genes were found: ATM, BRCA1, BRCA2, CHEK2, and PALB2." (PMID 35885460, 2022). "BRCA1 and BRCA2 have been identified in the ovarian cancer cluster region in or near exon 11, and in the breast cancer cluster region in multiple regions other than exon 11 so far." (PMID 36010882, 2022). "BRCA1 and BRCA2 genes are tumor suppressor genes that help repair DNA damage to suppress breast cancer tumorigenesis." (PMID 35373393, 2022). "We designed a rapid, digital pathway, supported by a genetics specialist hotline, for delivery of germline testing of BRCA1/BRCA2/PALB2 (BRCA-testing), integrated into routine UK NHS breast cancer care." (PMID 35868849, 2022). "Among other genes with a prevalence of PVs >1% were APC (1.12%), involved in hereditary colorectal cancer, the breast cancer genes PTEN and BRCA1 (1.61%, 1.06%), and FANCA (1.04%), involved in Fanconi anemia." (PMID 34255164, 2021). "Following the discovery of BRCA1 and BRCA2, several breast cancer genes with various degree of penetrance were identified." (PMID 33649982, 2021). "In the analyses, 6,591 BRCA1 and 4,208 BRCA2 heterozygotes of European ancestry who had developed an invasive first primary breast cancer before entry in CIMBA were identified." (PMID 34113011, 2021). "The tumor suppressor protein, BRCA1 and a histone demethylase called Jumonji Domain Containing 1C (JMJD1C), commonly reduced or lost in breast cancer are also suppressed in the E1-expressing cells." (PMID 34968392, 2021). "We found that in breast cancer cells, the mitochondrial targeting reagents, which all induce mitochondrial depolarization along with PINK1 upregulation, induced proteasomal BRCA1 degradation." (PMID 33888730, 2021). "For this objective, they chose breast cancer (BC) and colorectal cancer (CRC) since there is prior work reporting the conflicting prognostic significance of BRCA1 in these cancers." (PMID 34966485, 2021).
breast cancer (continued). "Only one each BRCA1 and BRCA2 deaths in carriers were breast cancer related in women on MRI screening (2/38)." (PMID 34312777, 2021). "Strikingly, BRCA1 and PINK1/Parkin expression were inversely correlated in cancerous mammary glands from breast cancer patients." (PMID 33888730, 2021). "We have reported a mean annual rate of incident prospective breast cancers in BRCA1/2 PV carriers of 1.6% (1.55% BRCA2, 1.73% BRCA1), consistent with currently published 69–72% risks by age 80 years when extrapolated over a 50-year risk period." (PMID 34312777, 2021). "For example, the use of archived specimens facilitated the establishment of the link between lung cancer and smoking, the identification of BRCA1 and BRCA 2 genes, and progress in breast cancer research." (PMID 35048019, 2021). "A significant interaction between the age at first breast cancer diagnosis and the ER-negative PRS313 was found for BRCA1 heterozygotes: HR per year = 0.99, 95% CI (0.99–1.00), p value = 0.025." (PMID 34113011, 2021). "In conclusion, the NCI site was suitable for cases of breast cancer except those related to (LCIS, DCIS, BRCA1, and BRCA2)." (PMID 34710987, 2021). "The interaction of BRCA1 and estrogen receptor α (ER-α) was observed in MCF-10A breast epithelial cells and MCF-7 breast cancer cells." (PMID 35008272, 2021). "The breast cancer subnetwork is found to contain (i) valid biomarkers including PIK3CA, PTEN, BRCA1, AR and EGFR; (ii) validated drug targets TOP2A, CDK4, HDAC1, IL6, BRCA1, HSP90AA1 and AR; (iii) synergistic drug targets EGFR and BIRC5." (PMID 35053185, 2021). "Accordingly, we collected 12 non-treated allograft mammary tumors and screened their entire transcriptomes using mRNA sequencing and the Cufflinks computational pipeline to predict which genes were associated with responsiveness following irradiation of Brca1-deleted tumors." (PMID 33767581, 2021). "We also identify a relationship between BRCA1 expression and race which could inspire investigation to explain a similarly elusive disparity of African American patients compared to other races in the incidence and mortality of breast cancer and colorectal cancer." (PMID 34611475, 2021). "Pan-HDAC inhibitors panobinostat and vorinostat/suberoylanilide hydroxamic acid (SAHA) cause hyperacetylation of nuclear HSP90, degrading DNA repair machinery proteins BRCA1, ATR, and CHK1 in breast cancer cells." (PMID 34696786, 2021).